KLRC1 (killer cell lectin like receptor C1)
Description:
Immune inhibitory receptor involved in self-nonself discrimination. In complex with KLRD1 on cytotoxic and regulatory lymphocyte subsets, recognizes non-classical major histocompatibility (MHC) class Ib molecule HLA-E loaded with self-peptides derived from the signal sequence of classical MHC class Ia molecules. Enables cytotoxic cells to monitor the expression of MHC class I molecules in healthy cells and to tolerate self. Upon HLA-E-peptide binding, transmits intracellular signals through two immunoreceptor tyrosine-based inhibition motifs (ITIMs) by recruiting INPP5D/SHP-1 and INPPL1/SHP-2 tyrosine phosphatases to ITIMs, and ultimately opposing signals transmitted by activating receptors through dephosphorylation of proximal signaling molecules. Key inhibitory receptor on natural killer (NK) cells that regulates their activation and effector functions. Dominantly counteracts T cell receptor signaling on a subset of memory/effector CD8-positive T cells as part of an antigen-driven response to avoid autoimmunity. On intraepithelial CD8-positive gamma-delta regulatory T cells triggers TGFB1 secretion, which in turn limits the cytotoxic programming of intraepithelial CD8-positive alpha-beta T cells, distinguishing harmless from pathogenic antigens. In HLA-E-rich tumor microenvironment, acts as an immune inhibitory checkpoint and may contribute to progressive loss of effector functions of NK cells and tumor-specific T cells, a state known as cell exhaustion. (Microbial infection) Viruses like human cytomegalovirus have evolved an escape mechanism whereby virus-induced down-regulation of host MHC class I molecules is coupled to the binding of viral peptides to HLA-E, restoring HLA-E expression and inducing HLA-E-dependent NK cell immune tolerance to infected cells. Recognizes HLA-E in complex with human cytomegalovirus UL40-derived peptide (VMAPRTLIL) and inhibits NK cell cytotoxicity. (Microbial infection) May recognize HLA-E in complex with HIV-1 gag/Capsid protein p24-derived peptide (AISPRTLNA) on infected cells and may inhibit NK cell cytotoxicity, a mechanism that allows HIV-1 to escape immune recognition. (Microbial infection) Upon SARS-CoV-2 infection, may contribute to functional exhaustion of cytotoxic NK cells and CD8-positive T cells. On NK cells, may recognize HLA-E in complex with SARS-CoV-2 S/Spike protein S1-derived peptide (LQPRTFLL) expressed on the surface of lung epithelial cells, inducing NK cell exhaustion and dampening antiviral immune surveillance.
Synonyms: CD159a; NKG2A; NKG2-A; NKG2-B; NKG2
Tractability: Antibody: a drug acting on it is in phase 2 or 3 trials; UniProt places it where antibodies can reach, with high confidence; its Gene Ontology location is reachable by antibodies, with high confidence; UniProt predicts a signal peptide or a membrane-spanning region; the Human Protein Atlas places it where antibodies can reach.
Gene: Protein-coding gene on chromosome 12 (10,442,264 to 10,454,685, reverse strand). Ensembl gene ENSG00000134545.
Subcellular location: Cell membrane
Subcellular location (Human Protein Atlas): Plasma membrane
Pathways (Reactome):
Immune System: Immunoregulatory interactions between a Lymphoid and a non-Lymphoid cell
Gene Ontology:
Molecular function: HLA-E specific inhibitory MHC class Ib receptor activity; inhibitory MHC class Ib receptor activity; MHC class I protein complex binding; protein antigen binding; protein binding; transmembrane signaling receptor activity; MHC class Ib receptor activity
Biological process: CD8-positive, gamma-delta intraepithelial T cell differentiation; natural killer cell inhibitory signaling pathway; negative regulation of natural killer cell mediated cytotoxicity; negative regulation of T cell mediated cytotoxicity; cell surface receptor signaling pathway; natural killer cell mediated immunity; positive regulation of natural killer cell mediated cytotoxicity; regulation of natural killer cell activation; stimulatory C-type lectin receptor signaling pathway; immune response-regulating cell surface receptor signaling pathway; immune system process; regulation of natural killer cell mediated cytotoxicity
Cellular component: plasma membrane; receptor complex; cell surface
Genetic constraint (gnomAD): Loss-of-function variants: 13 observed, 16.72 expected, observed/expected ratio (o/e) 0.78, 90% interval 0.5 to 1.24. The upper end of that interval is the gene's LOEUF score, 1.24, which puts it in group 5 of 6, group 1 being the genes least tolerant of losing a copy. Missense variants: 166 observed, 210.23 expected, observed/expected ratio (o/e) 0.79, 90% interval 0.69 to 0.9. Synonymous variants: 52 observed, 70.79 expected, observed/expected ratio (o/e) 0.73, 90% interval 0.59 to 0.93.
Homologues: Orthologues: chimpanzee KLRC1 (98% identical), rat Klrc1 (45% identical), mouse Klrc1 (44% identical), rat Klrc2 (38% identical), rat Klrc3 (38% identical), mouse Klrc2 (36% identical), mouse Klrc3 (35% identical), mouse Klre1 (23% identical), mouse Klri1 (22% identical), rat Klre1 (21% identical), rat Klri1 (21% identical), rat Klri2 (21% identical), and 11 more. Paralogues in human: KLRC2 (76% identical), KLRC3 (69% identical), KLRC4 (43% identical), CLEC12B (26% identical), CLEC7A (23% identical), KLRD1 (23% identical), CLEC12A (21% identical), KLRB1 (21% identical), CLEC9A (20% identical), KLRG1 (20% identical), KLRK1 (19% identical), OLR1 (19% identical), and 11 more.
Diseases named in the same sentence as KLRC1 in open-access papers:
KLRC1 is named in the same sentence as 151 diseases in open-access papers, as found by Europe PMC text mining. Sharing a sentence is not in itself a finding about the gene and the disease. The quoted sentences say what the papers report.
COVID-19 (77 papers, 2020 to 2025). A disease caused by infection with severe acute respiratory syndrome coronavirus 2. "In COVID-19, the expression of the inhibitory marker KLRC1 (also known as NKG2A) leads to decreased NK cells cytotoxic activity by affecting the IFNγ and TNFα pathways." (PMID 34603282, 2021). "KLRC1 (alias NKG2A) expression, in SARS-CoV-2 infected patients was suggested to correlate with functional exhaustion of cytotoxic lymphocytes and with a severe COVID-19 outcome." (PMID 38321133, 2024).
melanoma (22 papers, 2012 to 2025). A malignant, usually aggressive tumor composed of atypical, neoplastic melanocytes. "In melanoma, tumor infiltrating NK cells expressed higher levels of the KLRC1 gene (encoding the inhibitory receptor NKG2A) than NK cells in peripheral blood." (PMID 40849493, 2025).
multiple myeloma (19 papers, 2012 to 2026). "In contrast, disruption of the NKG2A-encoding killer cell lectin-like receptor C1 (KLRC1) has enhanced NK cell-mediated anti-tumor responses against multiple myeloma." (PMID 40292231, 2025). "CRISPR-edited NK cells with reduced expression of the inhibitory KLRC1 locus showed improved anti-myeloma cytolytic activity in vitro, and further study is needed for the clinical utility of ex vivo NK cell engineering in myeloma." (PMID 36389674, 2022).
lung carcinoma (13 papers, 2019 to 2026). "KLRC1 (or NKG2A) is an inhibitory receptor for both CD8 + cytotoxic T cells and NK cells and is predominantly expressed by CD8 + T cells in human lung cancer where their presence is correlated with the progression of chronic infection and cancer." (PMID 40585258, 2025). "The fractions of CD8+ T cells in two lung cancer subtypes were comparable with that in each other, but the Effector cells were enriched in LUAD, and cytotoxic, exhausted, GZMK+ Effector as well as KLRC1+ Effector cells were abundant in LUSC." (PMID 36008393, 2022).
lymphoma (12 papers, 2015 to 2025). A malignant (clonal) proliferation of B- lymphocytes or T- lymphocytes which involves the lymph nodes, bone marrow and/or extranodal sites. "Preclinical and clinical investigations have provided evidence that CD94/KLRC1 inhibition is a viable therapeutic option for numerous tumors, including chronic lymphoid leukemia and lymphoma." (PMID 36532059, 2022).
head and neck cancer (9 papers, 2016 to 2023). A primary or metastatic malignant neoplasm affecting the head and neck. "However, the expression level of KLRC1 was significantly higher in head and neck cancer, kidney renal clear cell carcinoma, and kidney renal papillary cell carcinoma compared with adjacent normal tissues." (PMID 32010126, 2019).
Autoimmunity (7 papers, 2019 to 2024). The occurrence of an immune reaction against the organism's own cells or tissues. "Notably, when focusing on individual interactions of the cDCa cluster, MHC class II-related transcripts (eg, CD74, HLA-E) were predicted to interact with surface molecules such as MIF or KLRC1 with immunomodulatory capacity and known association to autoimmunity." (PMID 34783307, 2021).
co-infection (7 papers, 2015 to 2022). "It indicated that KLRC1 might play roles in the H1N1-SS2 co-infection." (PMID 25906258, 2015).
psoriasis (7 papers, 2011 to 2025). An autoimmune condition characterized by red, well-delineated plaques with silvery scales that are usually on the extensor surfaces and scalp. "CXXC5, KLRC1, along with five additional genes, are linked to a reduced risk of psoriasis." (PMID 41328434, 2025). "The seven genes span established–emerging–novel tiers: PRF1 and KLRC1/KLRD1 are established in psoriasis immunity; SLFN5 is a recently reported systemic inflammatory marker; BIN2/CXXC5/CAPN12 lack prior links, suggesting novelty." (PMID 41328434, 2025). "Additional Mendelian randomization analysis pinpointed seven marker genes linked to psoriasis: BIN2, CAPN12, CXXC5, KLRC1, KLRD1, PRF1, and SLFN5." (PMID 41328434, 2025). "Monalizumab is known to inhibit NKG2A, a receptor protein encoded by KLRC1, whose expression is increased in lymphocytes of psoriasis patients." (PMID 37511476, 2023). "By integrating single-cell RNA sequencing with MR analysis, we identified seven psoriasis-related genes (BIN2, CAPN12, CXXC5, KLRC1, KLRD1, PRF1, and SLFN5) that are highly expressed in CD4+ T cells." (PMID 41328434, 2025). "KLRC1, KLRD1, PRF1, BIN2, and SLFN5 showed enrichment concentrated in immune-inflammatory modules—including IL-17 signaling, the TNF/NF-κB axis, and innate immune sensor pathways (NOD-, RIG-I-, and Toll-like receptors)—consistent with psoriasis-relevant Th17/innate activation." (PMID 41328434, 2025). "Because of such prior evidence, KLRC1 and KLRD1 are not novel to psoriasis: they have been studied and recognized as part of the disease’s immune dysregulation." (PMID 41328434, 2025).
endometriosis (6 papers, 2019 to 2024). The growth of functional endometrial tissue in anatomic sites outside the uterine body. "Among these genes, three (RGPD2, LTB, and KLRC1) exhibited distinct expression profiles between control and endometriosis-derived PBMCs." (PMID 39684780, 2024). "Moreover, it has been previously proposed that the KLRC1/HLA-E axis is involved in a hypothetical escape mechanism in which endometriosis ectopic expression of HLA-E inhibits NK cytotoxic activity." (PMID 39684780, 2024). "Whether upregulation of KLRC1 affects peripheral Vδ2-T cell activity in women with endometriosis remains to be investigated." (PMID 39684780, 2024). "Comparison between participants without endometriosis (n = 5) and participants with endometriosis (n = 4) with high serum JUP values (>220 ng/mL) identified nine DEGs (HBB, HBA1, HBA2, and RGPD2 in CD14+ monocytes; CH25H, HBB, LTB, and KLRC1 in γδt; IFIT2 in NK-CD56bright and JUN in Treg)." (PMID 39684780, 2024).
gastric cancer (6 papers, 2013 to 2025). A primary or metastatic malignant neoplasm involving the stomach. "For example, gastric cancer cells and many immune cell subtypes can interact with cytotoxic/exhausted CD8+ T cells and/or NK cells via HLA-E-KLRC1/KLRC2, suggesting that the anti-KLRC1 antibody may be a potential therapeutic option in gastric cancer." (PMID 41316282, 2025).
glioma (6 papers, 2013 to 2025). A benign or malignant brain and spinal cord tumor that arises from glial cells (astrocytes, oligodendrocytes, ependymal cells). "KLRC1, an inhibitory receptor for the non-classical MHC class I molecule HLA-E, has been involved in the inhibition of innate anti-glioma immune responses." (PMID 23472076, 2013).
Sepsis (6 papers, 2012 to 2025). Sepsis is defined as life-threatening organ dysfunction caused by a dysregulated host response to infection. "Although we observed increased NK frequencies in CCI, we have previously demonstrated via scRNA-seq analysis that cytotoxic genes (KLRC3, KLRC1, and KLRG1) of NK cells were downregulated in patients with late sepsis (CCI and rapid recovery) (n=4), suggesting dysregulation of these cells." (PMID 39691721, 2024).
bladder tumors (3 papers, 2023 to 2024). "Examination of invasive bladder tumors in TCGA (n = 408, initial bladder cancer patient cohort) showed that KLRC1 was either absent or expressed at very low levels in most bladder tumors." (PMID 36583228, 2023).
invasive breast carcinoma (3 papers, 2019 to 2025). A carcinoma that infiltrates the breast parenchyma. "KLRC1 expression was significantly lower in most of the tumors compared with adjacent normal tissues, such as breast invasive carcinoma, colon adenocarcinoma, liver hepatocellular carcinoma, LUAD, LUSC, PRAD, rectum adenocarcinoma, and uterine corpus endometrial carcinoma." (PMID 32010126, 2019).
vitiligo (2 papers, 2022 to 2024). Generalized well circumscribed patches of leukoderma that are generally distributed over symmetric body locations and is due to autoimmune destruction of melanocytes. "In addition, NK cells receptors, including natural killer cell triggering receptor (NKTR), killer cell lectin-like receptor C1 (KLRC1), CCL20, and NK cell-related cytokines such as TNFα and IL-15, are also increased in perilesional skin in patients with vitiligo." (PMID 35884944, 2022).
malaria (1 paper, 2020). Malaria is a serious and sometimes fatal disease caused by a parasite that commonly infects a certain type of mosquito which feeds on humans. "Klrd1, Klrc1, and Klrc3 reveal similar expression courses in response to malaria and to vaccination." (PMID 33202767, 2020).
tumor (387 papers, 2010 to 2026). "In contrast to TCGA LGG dataset, high tumor expression of KLRC1 and KLRC2 in CGGA LGG patients were associated with improved prognosis, but not KLRC3, KLRC4 or KLRK1." (PMID 34539622, 2021). "High tumor expression of KLRC1 and KLRC2 were also associated with improved survival in the CGGA LGG patient cohort, but not KLRK1, KLRC2 or KLRC4." (PMID 34539622, 2021). "Studies have demonstrated that blocking the KLRC1/HLA-E pathway in PC significantly enhances the anti-tumor activity of effector cells, thereby suppressing tumor progression." (PMID 40486509, 2025). "KLRC1 expression in SKCM is associated with immune cell infiltration, highlighting its role in immune surveillance and tumor microenvironment modulation." (PMID 41574107, 2025). "CRISPR-mediated KLRC1 gene editing not only targets the NKG2A/HLA-E IC but also enhances NK cell cytotoxic responses against HLA-E-positive tumor cells by augmenting NKG2C function." (PMID 40463500, 2025). "IFN-γ, secreted in the TME, promotes HLA-E expression on the tumor cell surface, which binds its specific receptor NKG2A, a major NK inhibitory receptor, encoded by the KLRC1 gene." (PMID 37675109, 2023). "To reduce NKG2A expression and its engagement with HLA-E on tumor cells, we used a CRISPR/Cas system to target KLRC1, the gene encoding for NKG2A, in NKAES." (PMID 37675109, 2023). "Remarkably, we observed that the transcript of NKG2A (Klrc1) was significantly more highly expressed in Tex cells of tumor than that in Tex cells of chronic viral infection." (PMID 35281793, 2022). "Consistently, greater amounts of the NKG2A transcript (Klrc1) were also observed in tumor‐specific Tex cells on both day 8 and day 21 as compared to these in chronic viral infection‐specific Tex cells." (PMID 35281793, 2022). "Conversely, expression of the genes associated with NK cell exhaustion, such as PDCD1, CTLA4, KLRC1, NR4A1, and SOCS3, was upregulated in tumor-infiltrating NK cells." (PMID 34535671, 2021). "The mRNA expression of CCL13 and KLRC1 in tumor tissues were significantly lower than that in the normal tissues." (PMID 34368124, 2021). "The gene Klrc1 (encodes NKG2A) is an inhibitory receptor in the KLR family, which is enhanced in tumor-infiltrating CD8 T cells." (PMID 33644036, 2020). "In the TIMER database, we found that although the transcript level of NKG2A (KLRC1) in the tumor was lower than that in adjacent normal tissue, the expression level of KLRC1 was related to the immune infiltration levels in different types of cancers." (PMID 32010126, 2019). "Thus, delving into the role of KLRC1 aligned with the potential acquisition of cytotoxicity by NK cells during tumor progression would be intriguing." (PMID 40164596, 2025). "Notably, the anti-tumor activities of natural killer (NK) cell family receptors, including KLRC1 and KLRC3, have been reported in different cancers and cancer phases, particularly in metastasis." (PMID 39227808, 2024). "Notably, mRNAs regulated by miR-141 were highly enriched for transcripts subject to cancer repression, and the miR-141-dependent regulation of many curtail tumor suppressor mRNAs, including the KLRC1, KLRC3, CAM3, CAM5, CAM6, and CAM7 was approved." (PMID 39227808, 2024). "In a previous study, which isolated mixtures from GC patient tumour tissue samples with at least 5% of NKG2A+ (KLRC1) tumour‐infiltrating T lymphocytes (TILs), HLA‐E‐KLRC1 interaction negatively affected IL2 receptor–dependent CD8+ TIL proliferation and contributed to CD8+ TIL dysfunciton." (PMID 35184420, 2022). "Of note, both of the NK sub-clusters from the high tumor infiltration group expressed high levels of KLRC1, a key inhibitory receptor for NK cells, which suggested that KLRC1 up-regulation may be a critical factor in the dysfunction of NK cells." (PMID 36532059, 2022). "Tumor-infiltrated NK cells expressed higher level of KLRC1(NKG2A) gene and KLRD1(CD94)." (PMID 34177887, 2021).